MAPK7 (mitogen-activated protein kinase 7)
Description:
Plays a role in various cellular processes such as proliferation, differentiation and cell survival. The upstream activator of MAPK7 is the MAPK kinase MAP2K5. Upon activation, it translocates to the nucleus and phosphorylates various downstream targets including MEF2C. EGF activates MAPK7 through a Ras-independent and MAP2K5-dependent pathway. As part of the MAPK/ERK signaling pathway, acts as a negative regulator of apoptosis in cardiomyocytes via interaction with STUB1/CHIP and promotion of STUB1-mediated ubiquitination and degradation of ICER-type isoforms of CREM (By similarity). May have a role in muscle cell differentiation. May be important for endothelial function and maintenance of blood vessel integrity. MAP2K5 and MAPK7 interact specifically with one another and not with MEK1/ERK1 or MEK2/ERK2 pathways. Phosphorylates SGK1 at Ser-78 and this is required for growth factor-induced cell cycle progression.
Synonyms: BMK1; ERK5; PRKM7; ERK4
Tractability: Small molecule: a structure with a bound ligand is known; a high-quality ligand is known; it belongs to a druggable protein family. PROTAC: it is named in the literature on targeted protein degradation; ubiquitination databases record sites on it; its protein half-life has been measured; a small molecule that binds it is known.
Target class: CMGC protein kinase ERK5; CMGC protein kinase group; Protein Kinase; CMGC protein kinase MAPK family; Kinase; Enzyme
Chemical probes: AX15836 (high quality), BAY-885 (high quality), INY-06-061 (high quality), JWG-071 (high quality), MKK7-COV-2 (high quality), MKK7-COV-3 (high quality), PD155981 (high quality), PPM-3 (high quality), XMD8-92 (high quality)
Gene: Protein-coding gene on chromosome 17 (19,377,721 to 19,383,544, forward strand). Ensembl gene ENSG00000166484.
Subcellular location: Cytoplasm; Nucleus; Nucleus, PML body
Subcellular location (Human Protein Atlas): Cytosol; Nucleoplasm
Pathways (Reactome):
Signal Transduction: ERK/MAPK targets; ERKs are inactivated; Gastrin-CREB signalling pathway via PKC and MAPK; Signalling to ERK5
Cellular responses to stimuli: Senescence-Associated Secretory Phenotype (SASP)
Developmental Biology: RET signaling
Gene Ontology:
Molecular function: mitogen-activated protein kinase binding; protein binding; enzyme inhibitor activity; MAP kinase activity; ATP binding; protein kinase activity; protein serine kinase activity; protein serine/threonine kinase activity
Biological process: cellular response to growth factor stimulus; cellular response to hydrogen peroxide; cellular response to laminar fluid shear stress; cellular response to transforming growth factor beta stimulus; negative regulation of endothelial cell apoptotic process; negative regulation of extrinsic apoptotic signaling pathway in absence of ligand; negative regulation of heterotypic cell-cell adhesion; negative regulation of oxidative stress-induced intrinsic apoptotic signaling pathway; negative regulation of response to cytokine stimulus; positive regulation of protein metabolic process; positive regulation of transcription by RNA polymerase II; adenylate cyclase-activating G protein-coupled receptor signaling pathway; intracellular signal transduction; MAPK cascade; negative regulation of inflammatory response; negative regulation of smooth muscle cell apoptotic process; signal transduction; cellular response to stress; negative regulation of apoptotic process
Cellular component: cytoplasm; cytosol; nucleoplasm; nucleus; PML body
Genetic constraint (gnomAD): Loss-of-function variants: 30 observed, 59.07 expected, observed/expected ratio (o/e) 0.51, 90% interval 0.38 to 0.69. The upper end of that interval is the gene's LOEUF score, 0.69, which puts it in group 2 of 6, group 1 being the genes least tolerant of losing a copy. Missense variants: 952 observed, 1,145.8 expected, observed/expected ratio (o/e) 0.83, 90% interval 0.79 to 0.88. Synonymous variants: 516 observed, 462.16 expected, observed/expected ratio (o/e) 1.12, 90% interval 1.04 to 1.2.
Homologues: Orthologues: chimpanzee MAPK7 (99% identical), macaque MAPK7 (98% identical), rabbit MAPK7 (93% identical), mouse Mapk7 (92% identical), rat Mapk7 (92% identical), pig MAPK7 (91% identical), guinea pig MAPK7 (89% identical), dog MAPK7 (87% identical), tropical clawed frog mapk7 (62% identical), zebrafish mapk7 (55% identical), Caenorhabditis elegans mpk-2 (24% identical), Caenorhabditis elegans F09C12.2 (18% identical). Paralogues in human: MAPK6 (22% identical), NLK (22% identical), MAPK3 (22% identical), MAPK1 (22% identical), MAPK11 (20% identical), MAPK14 (20% identical), MAPK15 (19% identical), MAPK8 (19% identical), MAPK10 (19% identical), MAPK9 (19% identical), MAPK4 (18% identical), MAPK13 (18% identical), and 7 more.
Diseases named in the same sentence as MAPK7 in open-access papers:
MAPK7 is named in the same sentence as 183 diseases in open-access papers, as found by Europe PMC text mining. Sharing a sentence is not in itself a finding about the gene and the disease. The quoted sentences say what the papers report.
breast cancer (76 papers, 2004 to 2026). A primary or metastatic malignant neoplasm involving the breast. "Suppression of MAPK7 has been shown to increase E-cadherin expression, thereby reducing migration and metastasis in breast cancer cells; in animal models, it regulates tumor growth and has been linked to metastatic risk in clinical studies of breast cancer." (PMID 41300329, 2025). "It has been previously shown that miR-143–3p plays a tumor-suppressive role in breast cancer by targeting MAPK7, a member of the MAP kinase family, which promotes signaling pathways involved in cell proliferation and anti-apoptosis in breast cancer." (PMID 39136001, 2024).
lung carcinoma (34 papers, 2012 to 2025). "Previous work in skin and lung cancer shows that MAPK7 promotes pro-tumour inflammation plus ‘M2-like’ polarisation of tumour-associated macrophages (TAMs)." (PMID 32655131, 2020). "Albeit within a relatively small number of lung cancer samples, gene amplification and overexpression of MAPK7 appeared to be a distinct molecular feature, as of the 3 samples, only 1 contained an EGFR L858R mutation and none had KRas mutation (data not shown)." (PMID 26040563, 2015). "They further proved that miR-24 promoted the viability, proliferation and cell cycle of lung carcinoma cells and inhibited cell apoptosis by binding to MAPK7 (mitogen-activated protein kinase 7)." (PMID 33123467, 2020). "Improved DNA repair capacity also increases the cellular radioresistance, as shown in lung cancer extracellular signal-regulated kinase 5 (ERK5), also known as MAPK7, which improved DNA repair via the homologous recombination repair pathway via the activation of Chk1." (PMID 36361653, 2022). "A network of interactions between proteins TUBB2B, MAPK7, TUBAL3, MAP2K5, and GJA1 (Cx43) suggests that reduced expression of MAPK and tubulin genes could be responsible for the attenuation of the gap junction pathway and insensitivity of lung cancer cells to cisplatin." (PMID 38351531, 2024).
melanoma (34 papers, 2015 to 2026). A malignant, usually aggressive tumor composed of atypical, neoplastic melanocytes. "We recently showed that five out of 479 melanoma patients harbor MAPK7 missense mutations, including P789S and A424S, two potential phosphorylation targets of C-terminus worth being characterized for their possible impact on ERK5 nuclear shuttling." (PMID 32023850, 2020). "Based on the findings above, to further illustrate the potential association between MAPK7 and efficiency of immunotherapy in melanomas, we constructed an independent validation cohort, containing 27 stage IV melanoma patients with anti-PD1 treatment (18 AMs, 6 CMs, 2 MMs)." (PMID 39039072, 2024). "Further analysis revealed that increased MAPK7-NFκB signaling accounts for the increase in T-cell infiltration in patients with melanoma." (PMID 39039072, 2024). "Based on these findings, we further constructed a xenograft melanoma mouse model using the MAPK7-KD-A375 stable cell line and used the KD-Control-A375 cell line as a control." (PMID 39039072, 2024). "In the present work, we show that ERK5 is an important mediator of HH-GLI signalling, as MAPK7 genetic depletion abolishes the increase in cell number induced by the activation of the HH-GLI pathway in melanoma cells." (PMID 34681917, 2021). "To this end, we evaluated the effect of MAPK7 silencing on HH-GLI-dependent proliferation induced by PTCH1 silencing in melanoma cells." (PMID 34681917, 2021). "In further support of a positive regulation of MAPK7 by GLI1 transcription factor, GLI1 silencing resulted in the reduction of MAPK7 mRNA in all three melanoma cell lines tested." (PMID 34681917, 2021). "The biological relevance of the regulation of ERK5 by the HH-GLI pathway is supported by the existence of a positive correlation between components of the HH-GLI pathway and MAPK7 mRNA in human melanomas." (PMID 34681917, 2021). "We recently showed that the extracellular signal-regulated kinase 5 (ERK5), encoded by the MAPK7 gene, plays a pivotal role in melanoma by regulating cell functions necessary for tumour development, such as proliferation." (PMID 34681917, 2021). "Moreover, for mice transplanted with MAPK7-KD-A375 cells, compared to PD-1 treatment alone, the combination of PRKDC and a PD-1 inhibitor significantly reduced tumor growth, confirming the potential of using a PRKDC inhibitor combined with an anti-PD-1 antibody for melanoma treatment in the future." (PMID 39039072, 2024).
prostate carcinoma (33 papers, 2007 to 2024). A carcinoma that arises from epithelial cells of the prostate gland. "As to miR-143, it was shown to target the mitogen-activated protein kinase 7 (ERK5), contributing to the inhibition of prostate cancer progression in mice." (PMID 32192092, 2020). "Several of the differentially expressed genes are known to play a critical role in prostate cancer, such as APC, MAPK7, or ZEB1." (PMID 22568834, 2012).
atherosclerosis (26 papers, 2012 to 2025). A disease characterized by the build-up of fatty material and calcium deposition in the arterial wall resulting in partial or complete occlusion of the arterial lumen. "Classical MAPKs, including ERK1/2 (MAPK3/1), JNK1‐3 (MAPK8‐10), p38 (MAPK11‐14), and ERK5 (MAPK7), have been proven to be activated by shear stress and predominantly participate in atherosclerosis progression." (PMID 39763069, 2025). "ERK5 (also called MAPK7) has pivotal roles in endothelial hemostasis and has a unique role in protection against atherosclerosis because it is both a kinase enzyme and a transcription co-activator." (PMID 31684100, 2019). "Moreover, the endothelial cell-specific deletion of MAPK7 and EZH2 in atherosclerosis-prone mice would further emphasize their relevance to atherogenesis in future perspective." (PMID 34493753, 2021).
hepatocellular carcinoma (20 papers, 2011 to 2025). A malignant tumor that arises from hepatocytes. "In particular, a direct involvement of ERK5 in hepatocellular carcinoma (HCC) has been established, where aberrant activation of MEK5/ERK5 signaling and ERK5/MAPK7 gene amplification have been reported and correlated with tumor progression and poor prognosis." (PMID 36650140, 2023). "Furthermore, in hepatocellular carcinoma (HCC), genetic dysregulation of MAPK7 expression through amplification of 17p11 is detectable in around 50 % of primary HCC tumors." (PMID 26040563, 2015).
glioma (19 papers, 2017 to 2024). A benign or malignant brain and spinal cord tumor that arises from glial cells (astrocytes, oligodendrocytes, ependymal cells). "From this we identified ERK5/MAPK7, which we subsequently validated using a range of siRNA and small molecule inhibitors within a panel of glioma cells." (PMID 33668183, 2021). "In human glioma, MAPK7 was found to be a direct target gene of miR-200b and was essential to the miR-200b-induced inhibition of glioma tumor growth, invasion and EMT." (PMID 29084594, 2017). "In addition, we explored the CGGA, an independent glioma database, and validated expressions of the CCNB1/CDC42/MAPK7/CD44 gene signatures in WHO grade II, III, and IV GBM tumors using the Analysis of variance (ANOVA), with p < 0.05 considered statistically significant." (PMID 35008426, 2022).
osteosarcoma (15 papers, 2015 to 2025). A usually aggressive malignant bone-forming mesenchymal neoplasm, predominantly affecting adolescents and young adults. "We cloned highly metastatic human osteosarcoma 143B cells with stably expressed short hairpin RNA (shRNA) to suppress MAPK7 expression." (PMID 40442778, 2025). "For instance, circ-0001721 accelerates the development of osteosarcoma via the miR-372-3p/MAPK7 axis, and circRNA circAGFG1 accelerates the progression of triple-negative breast cancer via regulating CCNE1, the sponge of miR-195-5p." (PMID 34568335, 2021). "In vitro assays have identified that miR-143 regulates proliferation, apoptosis, and migration of osteosarcoma cells via targeting multiple key molecules, such as MAPK7 and FOS-Like antigen 2 (FOSL2) 18-20." (PMID 33850470, 2021). "MiR-143 can suppress gastric cancer cell migration and metastasis by inhibiting MYO6 and EMT; it can also regulate the proliferation and migration of osteosarcoma through MAPK7." (PMID 31976313, 2020). "In osteosarcoma, tumour derived MAPK7 was shown to promote F4/80 + M2 TAM polarisation." (PMID 40442778, 2025). "circ_0001721 promotes the progression of osteosarcoma through the miR-372-3p/MAPK7 axis." (PMID 36159567, 2022). "DUSP1 gene silencing has been shown to increase the expression of MAPK7 and MAPK8 transcripts in osteosarcoma cells suggesting reciprocal actions between them." (PMID 31035605, 2019). "Mutant osteosarcomas lacking MAPK7 through stably expressed RNAi failed to metastasise in vivo." (PMID 40442778, 2025).
diabetes (13 papers, 2010 to 2025). "On the other hand, the MAPK7 pathway is involved in diabetes development." (PMID 40864764, 2025).
lung adenocarcinoma (8 papers, 2019 to 2024). A carcinoma that arises from the lung and is characterized by the presence of malignant glandular epithelial cells. "The MAPK7 (called also ERK5) inhibitor XMD8-92, suppressed CSCs formation in lung adenocarcinoma and glioblastoma." (PMID 37726810, 2023).
glioblastoma (7 papers, 2017 to 2024). The most malignant astrocytic tumor (WHO grade IV). "Moreover, CCNB1, MAPK7, CD44, and CDC42 oncogenes have been associated with patients’ clinical outcomes in glioblastoma and it has been identified in simulation studies for druggable candidates of SJ10." (PMID 39409884, 2024).
ovarian cancer (7 papers, 2013 to 2025). A primary or metastatic malignant neoplasm involving the ovary. "Moreover, pcDNA-MAPK7-transfected ovarian cancer cell lines displayed a stark increase in invasiveness and migration due to type II collagen upregulation, which was subsequently reversed through a MAPK7 silencing approach." (PMID 35053510, 2022).
gastric cancer (6 papers, 2010 to 2022). A primary or metastatic malignant neoplasm involving the stomach. "Mitogen-activated protein kinase 7 (MAP2K7) is an important tumor suppressor in gastric cancer, and frequent loss-of-function mutations activate the JNK pathway." (PMID 36439494, 2022). "CCT3 augments the viability of gastric cancer cells by modulating cell cycle proteins, including mitogen-activated protein kinase 7, cyclin D3, and cyclin-dependent kinases." (PMID 35773623, 2022).
non-small cell lung carcinoma (6 papers, 2012 to 2024). A group of at least three distinct histological types of lung cancer, including non-small cell squamous cell carcinoma, adenocarcinoma, and large cell carcinoma. "To explore MAPK7 tumor expression profiles in Asian cancer patients, we collected 74 non-small cell lung cancers and 95 squamous esophageal cancers of Chinese origin." (PMID 26040563, 2015).
heart failure (5 papers, 2016 to 2023). Inability of the heart to pump blood at an adequate rate to meet tissue metabolic requirements. "Given that Mapk7-cko mice exhibited impaired cardiac insulin sensitivity and cardiac function 1 week post-MI, we explored further evidence on whether MAPK7 restoration could slow down the progression of cardiac insulin resistance and heart failure in Mapk7-cko hearts stressed with ischemia." (PMID 32223896, 2020). "In a further attempt to obtain functional evidence supporting the proposed mechanisms responsible for MAPK7 regulation of CEBPβ signaling, we carried out rescue experiments on Mapk7-cko mice to evaluate whether overexpression of CEBPβ could prevent MAPK7 ablation-induced heart failure post-MI." (PMID 32223896, 2020).
ischemia (5 papers, 2020 to 2023). A hypoperfusion of the BLOOD through an organ or tissue caused by a PATHOLOGIC CONSTRICTION or obstruction of its BLOOD VESSELS, or an absence of BLOOD CIRCULATION. "In order to determine whether MAPK7 absence is a direct cause of cardiac insulin resistance, Mapk7-cko and their control littermates (Mapk7flox) were subject to short-term ischemia (one week)." (PMID 32223896, 2020). "We next attempted to examine the glucose uptake pathway in Mapk7-cko hearts under ischemia." (PMID 32223896, 2020).
sarcoma (5 papers, 2020 to 2026). A usually aggressive malignant neoplasm of the soft tissue or bone. "To fully investigate the role of ERK5 in our murine sarcoma-derived cell lines, we used specific shRNA targeting the murine Mapk7 gene." (PMID 35884568, 2022).
small cell lung carcinoma (5 papers, 2020 to 2024). Small cell lung cancer (SCLC) is a highly aggressive malignant neoplasm, accounting for 10-15% of lung cancer cases, characterized byrapid growth, and early metastasis. "Moreover, MAPK7 and its upstream activator, MAP2K5, are also known to control lipid metabolism in small cell lung cancer cells." (PMID 36232834, 2022).
bone cancer (4 papers, 2020 to 2024). A primary or metastatic malignant neoplasm affecting the bone or articular cartilage. "Our results implicate a newly discovered, multidimensional MAPK7/MMP9 signalling hub in primary bone cancer metastasis that is clinically actionable." (PMID 32655131, 2020). "This approach with comparisons applied to data collected from cell line models, clinical samples and xenograft mouse models revealed mitogen-activated protein kinase 7/matrix metallopeptidase 9 (MAPK7/MMP9) signalling as a driver for primary bone cancer metastasis." (PMID 32655131, 2020).